NOTCH2 (notch receptor 2)
Diseases named in the same sentence as NOTCH2 in open-access papers (continued):
Sharing a sentence is not in itself a finding about the gene and the disease.
preeclampsia (4 papers, 2015 to 2021). Preeclampsia is a hypertensive disorder of pregnancy that is characterized by new-onset hypertension with proteinuria presenting after 20 weeks of gestation, and depending on mild or severe forms may initially present with severe headache, visual disturbances, and hyperreflexia. "The results of a previous study showed an obvious upregulation of Notch3 expression, and a downregulation of Notch2 expression, in placentas from patients with early onset severe preeclampsia compared with those in normal placentas." (PMID 28606936, 2017). "The expression of Notch2 is decreased, and that of Notch3 is generally increased, in the placental tissues from patients with preeclampsia compared to those with normal placental tissues, according to previous experiments." (PMID 28606936, 2017). "It is hypothesized that abnormal expression of Notch2 and Notch3, and the resulting effects on trophoblast cells, might lead to the early onset of severe preeclampsia and other obstetric disorders." (PMID 28606936, 2017). "Taken together, our study results provide evidence that Notch2 and Notch3 are able to suppress proliferation by inducing cell cycle arrest, and promote the migration and invasion of trophoblast cells, through which they might participate in the pathogenesis of preeclampsia." (PMID 28606936, 2017). "However, the mechanisms by which Notch2 and Notch3 are related to preeclampsia remain unknown." (PMID 28606936, 2017). "Previous research showed that Notch2 expression decreased, and Notch3 was overexpressed, in the placentas of patients with preeclampsia compared with normal placentas, which indicate that Notch2 and Notch3 may play important roles in the pathology of preeclampsia." (PMID 28606936, 2017). "Roles for the Notch signaling pathway and the storkhead box 1 (STOX 1) transcription factor have also been suggested since Notch 2-null mice exhibited a decrease in spiral artery diameter and placental perfusion, while overexpression of STOX 1 in mice led to a preeclampsia phenotype of hypertension." (PMID 32548805, 2020).
acute myeloid leukemia (3 papers, 2018 to 2024). Acute myeloid leukemia (AML) is a group of neoplasms arising from precursor cells committed to the myeloid cell-line differentiation. "In a subsequent study, it has been shown that Notch reactivation (especially Notch2) within the acute myeloid leukemia (AML)-initiating cells was sufficient to drive their cell cycle arrest, differentiation, and apoptosis without inducing T-ALL." (PMID 33585446, 2020).
adenoma (3 papers, 2017 to 2020). A neoplasm arising from the epithelium. "Comparatively, in adenomas, ≥2-fold Notch3 expression was detected in 56% followed by Notch1 (44%), Notch4 (33%), and Notch2 (11%), while for ligand Jag1, mRNA was overexpressed in 33%, Jag2, Dll1, and Dll3 in 11%, whereas Dll4 was not expressed in adenomas." (PMID 32211044, 2020). "KrasG12D upregulates expressions of Notch2, Notch3, Notch4, Jag1 and downstream target genes Hes1, Hey1 and Hey2, and deletion of Jag1 partially suppresses KrasG12D-induced adenoma development." (PMID 29142904, 2017).
autoimmune disease (3 papers, 2022 to 2025). A disorder resulting from loss of function or tissue destruction of an organ or multiple organs, arising from humoral or cellular immune responses of the individual to their own tissue constituents. "Nevertheless, there are many controversies concerning Notch2’s role in pathological conditions, particularly in autoimmune diseases, characterized by sustained and chronic inflammation." (PMID 41517433, 2025). "Alterations in Notch2 expression, in particular, appears to be correlated with the onset of various autoimmune diseases." (PMID 41517433, 2025). "Overall, CD4+Notch2+Foxp3lo T cells support Treg cell expansion, thereby promoting recovery from autoimmune diseases." (PMID 40702356, 2025). "Notch2 plays a major role in IL-19-mediated maturation of lung dendritic cells, which may have potential implications for the involvement of antigen-presenting cells in autoimmune diseases." (PMID 35846128, 2022). "In primary Sjögren’s disease (pSjD), an autoimmune disorder characterized by chronic inflammation, the role of ADAM17 has been extensively explored, but a correlation with Notch2 has not yet been evaluated." (PMID 41517433, 2025).
Burkitt lymphoma (3 papers, 2014 to 2021). A rare form of malignant mature B-cell non-Hodgkin lymphoma. "MTT assay was used to assess the growth rates of the stably-infected DLBCL and Burkitt's lymphoma cell lines, and the results showed that mt Notch2 cells grew much faster than wt Notch2 cells and pLVX cells." (PMID 25314575, 2014). "In the three DLBCL cell lines, wt Notch2 cells grew faster than pLVX cells; while in Burkitt's lymphoma cell lines, similar results were only found in Raji and Ramos cell lines." (PMID 25314575, 2014).
COVID-19 (3 papers, 2021 to 2025). A disease caused by infection with severe acute respiratory syndrome coronavirus 2. "Among the testable tissues, we found that NOTCH2 expression in the colon and esophagus increased the risk of COVID-19, with larger effect sizes and significance compared with the effect estimate from blood eQTL." (PMID 35602207, 2021). "Besides NOTCH2, we found that the expression of the other three paralogs also increases the risk of COVID-19 in a tissue-specific manner." (PMID 35602207, 2021). "Among NOTCH1-4, only NOTCH2 significantly (P = 0.007) increased during aging, suggesting that the age-related increase of COVID-19 risk may partially be mediated through the increase in NOTCH2 expression." (PMID 35602207, 2021). "Hence, the ability of 2-pyridone PIM1 inhibitor to normalize the expression of Notch 1 and reduce the expression of Notch 2 below the control levels could provide a mechanism by which 2-pyridone PIM1 inhibitor could be effective in treatment of COVID-19." (PMID 37211584, 2023). "We observed a relatively large effect size (43% increased risk of infection for every one standard deviation higher NOTCH2 expression), suggesting that NOTCH2 may be a desirable target in COVID-19, as well as a marker of a population with a higher potential risk of infection." (PMID 35602207, 2021).
endometriosis (3 papers, 2021 to 2025). The growth of functional endometrial tissue in anatomic sites outside the uterine body. "A positive correlation between circ_0061140 and Notch homolog 2 (Notch2) was demonstrated in endometriosis." (PMID 34122342, 2021). "Additionally, circ_0067301 and circ_0061140 can induce the expression of different members of the Notch family, Notch1 and Notch2, in endometriosis." (PMID 41283360, 2025). "In addition, two circRNAs (circ_0067301 and circ_0061140) induced the expression of different members of the Notch family, Notch1 and Notch2 in endometriosis." (PMID 34122342, 2021). "Moreover, circ_0061140 could induce endometriosis progression via miR-140-3p-Notch2 axis." (PMID 34122342, 2021).
glomerulosclerosis (3 papers, 2018 to 2020). A hardening of the kidney glomerulus caused by scarring of the blood vessels. "Given the differential role of Notch1 and 2, it is likely that the loss of Notch1 and maintenance of Notch 2 in podocytes has a superior effect on glomerulosclerosis and proteinuria than the podocyte-specific loss of the pan-Notch regulator Rbpjk." (PMID 33519447, 2020). "Consistent with previous findings, podocyte-specific expression of the active Notch1 intracellular domain caused albuminuria and glomerulosclerosis, while mice with overexpression of the Notch2 intracellular domain did not exhibit phenotypic alterations." (PMID 33519447, 2020).
glomus tumor (3 papers, 2022 to 2024). A rare benign or malignant mesenchymal neoplasm arising from cells that resemble the modified smooth muscle cells of the glomus body. "CARMN-NOTCH2 Fusion: In glomus tumors of the upper digestive tract, CARMN (Cardiac Mesoderm Enhancer-Associated Non-Coding RNA) ncRNA can form a fusion with NOTCH2, and the resulting chimeric transcript was linked with gain-of-function for the latter gene." (PMID 38919532, 2024).
Hyperglycemia (3 papers, 2021 to 2025). An increased concentration of glucose in the blood. "NOTCH2 participated in inhibiting osteogenesis caused by hyperglycemia." (PMID 34149403, 2021). "Notch2 is a target of miR-18a-5p which recently confirmed its antifibrotic role via the suppression of Notch2 and consequent inhibition of hyperglycemia-induced EndMT in human aortic valvular endothelial cells (HAVECs)." (PMID 34095153, 2021).
Hypertension (3 papers, 2013 to 2024). The presence of chronic increased pressure in the systemic arterial system. "A significant decrease in the immunoreactivity of NOTCH2 and JAG2 proteins has been observed before in human term placentas complicated by fetal growth restriction (FGR) or hypertension, compared to normal placentas." (PMID 25962154, 2015).
malignant glioma (3 papers, 2007 to 2022). A grade III or grade IV glioma arising from the central nervous system. "We further propose the combination of two NOTCH2 genetic markers to provide sharp diagnostic and prognostic accuracy of malignant gliomas." (PMID 17593975, 2007). "Notch2 is important in both carcinogenesis and the development of the most malignant gliomas." (PMID 35586496, 2022). "Specifically in the context of malignant glioma, these include NOTCH1, NOTCH2, MET, and CDK6." (PMID 22479456, 2012).
meningioma (3 papers, 2017 to 2025). A generally slow growing tumor attached to the dura mater. "As a result, most of the previously reported meningioma mutations (NF2, TRAF7, NOTCH2, SMARCB1, CHEK2 and AKT1) were also detected in this study." (PMID 28177878, 2017). "The NOTCH2 c.7223T>A variant is also pathogenic (score 0.85) and has already been described in meningioma, a primary non-malignant CNS tumor." (PMID 33503190, 2021).
Nephropathy (3 papers, 2018 to 2025). A nonspecific term referring to disease or damage of the kidneys. "Together, these findings demonstrate that CCL5 is upregulated in podocytes in both human and mouse models of glomerular injury, with its expression in ADR-induced nephropathy following a pattern similar to Notch2 activation." (PMID 40986444, 2025). "Transcript analysis of mouse kidney disease models, including folic-acid (FA)–induced nephropathy, unilateral ureteral obstruction (UUO), or apolipoprotein L1 (APOL1)-associated kidney disease, indicated that Jag1 and Notch2 levels were higher in all analyzed kidney fibrosis models." (PMID 30226866, 2018). "Since CCL5 is induced in ADR-treated podocytes, similar to Notch2 activation, we investigated whether CCL5 plays a protective role in ADR-induced nephropathy by assessing podocyte apoptosis." (PMID 40986444, 2025).
pituitary adenomas (3 papers, 2017 to 2025). "Egfl7 could also promote pituitary adenomas proliferation and invasion via the Notch2/DLL3 signaling pathway." (PMID 37480091, 2023). "Furthermore, NOTCH2 expression was found increased in the Hoechst high efflux population of stem cells named the side population (SP) in human pituitary adenomas, but reduced levels of NOTCH2 mRNA were described in pituitary adenomas compared to craniopharyngiomas." (PMID 28915655, 2017).
polycystic kidneys (3 papers, 2017 to 2023). "The variable expression of NOTCH2 justifies the frequent association of serpentine fibula and polycystic kidneys as nothing but another manifestation of HCS and not an independent syndrome." (PMID 32854429, 2020).
polycystic ovary syndrome (3 papers, 2015 to 2025). A disorder that manifests as multiple cysts on the ovaries. "A control experiment among patients with polycystic ovary syndrome (PCOS) showed that, compared with individuals without PCOS, the eggs of patients with PCOS extracted high Notch-2 in oocyte complexes; here, Notch-3, Jagged-1, and Jagged-2 gene expression decreased significantly." (PMID 38003436, 2023).
psoriasis (3 papers, 2016 to 2025). An autoimmune condition characterized by red, well-delineated plaques with silvery scales that are usually on the extensor surfaces and scalp. "Midkine is a heparin-binding growth factor broadly expressed in inflammatory diseases; recent studies have shown that MK regulates VEGF-A expression via the Notch2/HES1/JAK2-STAT5A signaling pathway, thereby exerting critical effects on angiogenesis in psoriasis." (PMID 40959079, 2025).
retinoblastoma (3 papers, 2016 to 2022). A malignant tumor that originates in the nuclear layer of the retina. "Moreover, miR-488-3p has been revealed to exhibit cancer-inhibiting effects by suppressing the expression of NOTCH2, such as significantly inhibiting the proliferation, invasion, and migration and cell cycle progression and inducing apoptosis in retinoblastoma." (PMID 35186188, 2022). "A series of canonical pathways, including those involved in Rb (Retinoblastoma)/E2F cell cycle (Rb, E2f2, E2f3, E2f5, Cdk6, DHFR), Notch (Dll1, Notch 2, Jag1), Wnt (Wnt, Axin2, Wisp2/Ccn5) and NF-κB (Ikbip) were found to participate in this network." (PMID 30742662, 2019). "Notch pathway components were present in WERI Rb1 and Y79 retinoblastoma lines, with Jag2 and DLL4 more highly expressed than other ligands, and Notch1 and Notch2 more abundant than Notch3." (PMID 27661116, 2016).
rheumatoid arthritis (3 papers, 2023 to 2025). A chronic, systemic autoimmune disorder characterized by inflammation in the synovial membranes and articular surfaces. "Therefore, Notch2 has been shown to be upregulated in inflammatory states that characterize diseases like rheumatoid arthritis (RA) and bacterial and viral infections." (PMID 41517433, 2025).
angiosarcoma (2 papers, 2018 to 2025). A malignant tumor arising from the endothelial cells of the blood vessels. "We identified mutations in both NOTCH1 (n = 19, 5.29%) and NOTCH2 (n = 19, 5.29%) in the database, consistent with prior findings of mutations in both human and animal forms of angiosarcoma." (PMID 41301029, 2025). "NOTCH1 specifically has been linked to cutaneous angiosarcomas, while NOTCH2 has been associated with visceral angiosarcomas with poorer survival than NOTCH1." (PMID 41301029, 2025).
Arthritis (2 papers, 2023 to 2025). Inflammation of a joint. "Previous work demonstrated that a NOTCH2 gain-of-function mutation sensitizes mice to the development of arthritis following DMM surgeries and to the osteolytic actions of TNFα." (PMID 40345585, 2025). "Bulk RNA-Seq confirmed that NOTCH2 enhanced signaling pathways associated with the inflammatory response, arthritis, fibrosis, and collagen degradation." (PMID 40345585, 2025). "Previous work demonstrated that a NOTCH2 gain-of-function sensitizes mice to the development of arthritis following destabilization of the medial meniscus surgeries." (PMID 37865314, 2023).
atopic dermatitis (2 papers, 2010 to 2022). "We demonstrate that skin-specific inactivation of Notch1 and Notch2 simultaneously, or RBP-J, induces the development of a severe form of atopic dermatitis (AD), characterized by acanthosis, spongiosis and hyperkeratosis, as well as a massive dermal infiltration of eosinophils and mast cells." (PMID 20174635, 2010).
Autoimmunity (2 papers, 2025). The occurrence of an immune reaction against the organism's own cells or tissues. "Thus, CD4+Notch2+Foxp3lo T cells function as immunoregulatory CD4+ T cells that play a central role in recovery from inflammation during autoimmunity." (PMID 40702356, 2025). "Not surprisingly, recent evidence points to Notch2 signaling as an important player in autoimmunity, characterized by sustained and chronic inflammation." (PMID 41517433, 2025).
benign hepatocellular adenoma (2 papers, 2018 to 2024). "Tumor-specific Notch2 deletion switched the tumor type in the Akt-YAP1 model from cHCC-CCA to a benign hepatocellular adenoma-like tumor at the expense of CCA." (PMID 39273023, 2024). "Deletion of Notch2 in AKT/Yap-induced tumors switched the phenotype from ICC to hepatocellular adenoma-like lesions, while inactivation of Notch1 in hepatocytes did not result in significant histomorphological changes." (PMID 29545603, 2018). "Strikingly, ablation of Notch2 resulted in mostly hepatocellular adenomas with some HCC lesions in the liver, while no ICC lesions could be detected." (PMID 29545603, 2018).
biliary atresia (2 papers, 2015). A rare, biliary tract disease characterized by progressive obliterative cholangiopathy of the intra- and extrahepatic bile ducts, occurring in the embryonic/ perinatal period, leading to severe and persistent neonatal jaundice and acholic stool. "Importantly, a NOTCH2 mutation has been reported in one case of Allagile Syndrome (autosomal dominant disorder whose main feature is bile duct paucity or even biliary atresia) where the patient also had kidney dysfunction manifestations including hematuria and proteinuria." (PMID 26179878, 2015).
breast adenocarcinoma (2 papers, 2009 to 2015). "Accordingly, a recent study demonstrates that activation of different Notch receptors in the human mammary adenocarcinoma cell line MDA-MB-231 drives dramatically opposing effects, leading to either increased apoptosis in the case of Notch2 or increased proliferation in the case of Notch4." (PMID 20011512, 2009).
cardiac hypertrophy (2 papers, 2022 to 2025). "In summary, gain-of-function mutations in Notch2 gene induce cardiac hypertrophy and diastolic dysfunction by disrupting ADSL-mediated AMP biosynthesis, and targeting purine nucleotide metabolism may represent an attractive therapeutic strategy for the treatment of cardiac diseases." (PMID 40104444, 2025). "Using a humanized mouse expressing the human N2ICD fragment in cardiomyocytes, we unveiled Notch2 overactivation results in cardiac hypertrophy, left ventricular diastolic dysfunction in mice with preserved EF." (PMID 40104444, 2025). "Taken together, the cardiomyocyte-specific overexpression of Notch2 intracellular domain (N2ICD) led to cardiac hypertrophy and an HFpEF-like phenotype in mice." (PMID 40104444, 2025). "Notably, the pro-ventricular hypertrophy effect of Notch2 is quite different from the functions of Notch1 and Notch3 in cardiac development, since mice lacking each of them develop HCM." (PMID 40104444, 2025). "Here, a murine model expressing the human Notch2 intracellular domain (hN2ICD) in cardiomyocytes (hN2ICD-TgCM) was generated and the mice spontaneously developed ventricular diastolic dysfunction with preserved ejection fraction and cardiac hypertrophy." (PMID 40104444, 2025). "Thus, excessive Notch2 signaling promotes cardiac hypertrophy and dysfunction by modulating purine nucleotide metabolism." (PMID 40104444, 2025). "NOTCH1, but not NOTCH2 blockade, blunted the development of cardiac hypertrophy and fibrosis, and preserved cardiac function in mice subjected to pressure overload." (PMID 35448087, 2022). "In the present study, we therefore examined the possibility that inhibition of NOTCH1 or NOTCH2 signaling in vivo in a situation of cardiac hypertrophy may facilitate the emergence of CMs from non-myocyte origins." (PMID 35448087, 2022).
cataract (2 papers, 2017 to 2025). Partial or complete opacity of the crystalline lens of one or both eyes that decreases visual acuity and eventually results in blindness. "The authors subsequently reported the lens phenotypes of Notch2 conditionally mutant mice, which exhibit severe microphthalmia, a disrupted fiber cell morphology, eventual loss of the anterior epithelium, fiber cell dysgenesis, denucleation defects, and cataracts." (PMID 29299142, 2017). "Specifically, we observed significant reductions in JAG1 and Notch receptors (Notch1, Notch2, and Notch3) in the LECs of cataract patients." (PMID 39796164, 2025).